HK2 (hexokinase 2)
Diseases named in the same sentence as HK2 in open-access papers (continued):
Sharing a sentence is not in itself a finding about the gene and the disease.
brain diseases (1 paper, 2025). "Studies demonstrated that HK-2 is involved in glycolytic flux and mitochondrial activity during maladaptive inflammation in brain diseases." (PMID 40746540, 2025).
cardiac disease (1 paper, 2019). "HK2, a rate-limiting enzyme in glycolysis, catalyzes the formation of glucose-6-phosphate from glucose and regulates the mitochondrial dysfunction in cardiac disease." (PMID 31109015, 2019).
cardiovascular diseases (1 paper, 2025). "Studies have provided evidence for the impact of HK2 expression levels on cardiovascular diseases, such as MI." (PMID 40342964, 2025).
digestive system cancer (1 paper, 2017). A primary or metastatic malignant neoplasm involving any part of the digestive system. "In summary, HK2 might act as a prognostic indicator and a potential therapeutic target of these digestive system cancers." (PMID 28415659, 2017). "To further investigate the prognostic impact of HK2 on digestive system cancers, we analyzed the correlation between HK2 expression and clinicopathological factors that may affected the survival outcomes." (PMID 28415659, 2017).
head and neck tumor (1 paper, 2019). "Reduced lactate levels after depletion of HK2 may contribute to its inhibitory effect on cell migration and invasion, owing to the observation that lactate can enhance the motility of head and neck tumor cells." (PMID 31212816, 2019).
infectious disease (1 paper, 2018). A disorder directly resulting from the presence and activity of a microbial, viral, or parasitic agent in humans. "Studies in some systems indicate that the HK2 isoform is the most up regulated isoform in activated T cells and in this report the relevance of this finding is evaluated in an infectious disease model." (PMID 29352298, 2018).
kidney diseases (1 paper, 2023). "In this study, we first demonstrated that HIF-1α CTAD could exert a protective role against hypoxia-induced kidney diseases through transcriptional regulation of HK2." (PMID 37225700, 2023).
peripheral neuropathy (1 paper, 2024). A disorder affecting the peripheral nervous system. "This perspective is adjacent to recent findings that upregulated glycolysis induced by increased expression of HK2 is one of the mechanisms responsible for peripheral neuropathy in T2DM." (PMID 39314314, 2024).
retinopathy (1 paper, 2021). "HK2 is a predominant HK isoform in insulin-sensitive tissues including the retinopathy." (PMID 35096809, 2021).
vasculopathy (1 paper, 2023). "Indeed, circulating monocytes and monocyte-derived macrophages from patients with fibroinflammatory vasculopathy are highly efficient in glucose import and are expressing higher glycolysis-associated genes (GLUT1, HK2, PKM2, LDH, c-myc, and HIF-1α) in comparison to healthy individuals." (PMID 37415975, 2023).
HK2 also shares sentences with these, for which no sentence is quoted: multiple myeloma (6 papers); squamous cell carcinoma (6); liver steatosis (4); systemic lupus erythematosus (4); liver disease (3); Acute hepatic porphyria (2); anaplastic astrocytoma (2); Astrocytoma (2); autoimmune disease (2); central nervous system lymphoma (2); cholangiocarcinoma (2); chronic myeloid leukemia (2); COVID-19 (2); cutaneous squamous cell carcinoma (2); endocervical adenocarcinoma (2); endothelial dysfunction (2); fungal infection (2); ovarian tumor (2); rectal cancer (2); adenomyosis (1); age (1); Alstrom syndrome (1); anaplastic oligoastrocytoma (1); anaplastic oligodendroglioma (1); Atherosclerotic lesion (1); autoimmune hepatitis (1); Autoimmunity (1); benign cystadenomas (1); cervical tumor (1); childhood asthma (1).
A further 85 diseases each share a sentence with HK2 in 1 paper.